FHOD1 (formin homology 2 domain containing 1)
Diseases named in the same sentence as FHOD1 in open-access papers (continued):
Sharing a sentence is not in itself a finding about the gene and the disease.
tumor (11 papers, 2013 to 2025). "Increasing evidence suggests that the aberrant expression of FHOD1 is associated with changes in the immune microenvironment of multiple tumor types, which provides new perspectives for understanding the mechanism of tumor immune escape." (PMID 40364836, 2025). "Studies have shown that FHOD1 expression is associated with lymphocyte infiltration in tumor." (PMID 40364836, 2025). "For the downregulated genes, Id1, Tor4a, Fam83d, Chst12, Fhod1, Sapcd2, and Gas2l3 are known as proliferative and metastatic oncogenes contributing to tumor progression." (PMID 40231790, 2025). "In tumor cells, FHOD1 exploits the PD-1/PDL1 pathway to evade immune surveillance, through the suppression of T-cell responses within the TME." (PMID 40364836, 2025). "Altogether this review provides an in-depth understanding of the role of FHOD1 in tumor immunosuppression." (PMID 40364836, 2025). "Specifically, FHOD1 can impair function of chemokine receptors that are supposed to direct immune cells to localize to the tumor site accurately." (PMID 40364836, 2025). "Based on this finding, we can further explore the potential role of FHOD1 in the tumor microenvironment." (PMID 40364836, 2025). "Our analysis not only reveals the potential mechanism of FHOD1 in tumor cell proliferation and invasion but also demonstrates its importance in tumor microenvironment." (PMID 40364836, 2025). "With further research, we expect to gain a more comprehensive understanding of the function of FHOD1 in tumor biology, which will help develop innovative and effective therapeutic strategies." (PMID 40364836, 2025). "Studies have shown that FHOD1 can not only regulate intracellular signals in tumor cells but also regulate various components of the tumor microenvironment (TME), such as T cells, B cells, cancer-associated fibroblasts (CAFs), some cytokines." (PMID 40364836, 2025). "In this exhaustive review, we elucidate the pivotal role of FHOD1 protein in tumor biology, with a specific focus on its regulatory mechanism in upregulating PDL1 expression through the EMT pathway." (PMID 40364836, 2025). "In conclusion, the role of FHOD1 in tumorigenesis and development cannot be ignored, as it regulates tumor cell behavior and remodels the immune microenvironment through multiple mechanisms." (PMID 40364836, 2025). "In this review, considering the pivotal role of FHOD1 in both tumor cells and TME, we aimed to summarize the functions and underlying mechanisms of FHOD1 acts in the communication between tumor cells and TME." (PMID 40364836, 2025). "Aberrant expression and dysfunction of the FHOD1 protein play a key role in tumor immunosuppression." (PMID 40364836, 2025). "Tumor cell FHOD1 expression strongly correlated with high numbers of tumor-infiltrating CD8 + lymphocytes." (PMID 34115237, 2021). "The possible relationship between FMNL1 and FHOD1 with the tumor immune infiltrating lymphocytes in GC is still largely unstudied." (PMID 34115237, 2021). "FHOD1 and FMNL1 proteins are expressed in the tumor cells of intestinal GC and significantly associate with clinical parameters without direct prognostic significance." (PMID 34115237, 2021). "Therefore, elucidating the precise role of FHOD1 in this process is important for the development of new tumor therapeutic strategies." (PMID 40364836, 2025). "Researchers have found that the upregulation of FHOD1 expression is closely related to the invasiveness of tumor cells, which may provide a new target for tumor therapy." (PMID 40364836, 2025). "FHOD1 is enhanced by the up-regulation of PDL1 expression during EMT, and a large body of literature has shown that upregulation of PDL1 expression causes autophagy in tumor fibroblasts." (PMID 40364836, 2025). "In addition, FHOD1 activated signaling pathways within the immune cells abnormally, resulting in their inability to recognize and destroy tumor cells effectively." (PMID 40364836, 2025).
tumor (continued). "For example, FHOD1 may play an important role in tumor immune escape by regulating certain key signaling molecules, particularly its effect on the expression of the immune checkpoint molecule PD-L1." (PMID 40364836, 2025). "Most tumor tissues from advanced grade and stage patients showed high levels of FHOD1." (PMID 37211949, 2023). "Based on these observations, we subsequently regarded the endothelial staining and plasma cells as internal positive controls for FHOD1 stainings in the tumor samples, and lymphocytes and muscle cells were, respectively, regarded as internal positive controls for FMNL1." (PMID 34115237, 2021). "Indeed, we found a correlation between tumor cell FHOD1 expression and high numbers of CD8 + lymphocytes." (PMID 34115237, 2021). "There was also a similar trend with FHOD1 expression in the central tumor part, but this association was not statistically significant (T3: 39.3% and T4: 35%, p = 0.069)." (PMID 34115237, 2021). "The analyses showed that tumors with intermediate or high tumor cell FHOD1 staining intensity harbored significantly higher numbers of CD8-positive cells (p = 0.039 in central and p = 0.003 in peripheral part) than tumors with negative or weak FHOD1 expression (respectively)." (PMID 34115237, 2021). "Interestingly, FHOD1 immunoreactivity was mild or absent in the well-differentiated areas of invasive cancer, indicating that the tumour bulk that consists of cellular areas with epithelial differentiation expresses little FHOD1." (PMID 24086398, 2013). "Furthermore, the upregulation of FHOD1 expression in tumor cells in tumor cells is not limited to the promotion of tumor cell proliferation and invasion, but also involves a complex network of signaling pathways that regulate the expression and function of immune molecules." (PMID 40364836, 2025). "Therefore, FHOD1 may indirectly affect tumor progression and immune evasion mechanisms by regulating EMT." (PMID 40364836, 2025). "Transcription factors play a key role in inducing FHOD1 expression during EMT, which subsequently promotes tumor cell proliferation, migration, and invasion, thereby accelerating tumourigenesis and progression." (PMID 40364836, 2025). "Here, we analyzed the expression of FHOD1 and FMNL1 in intestinal-type tumor samples of the stomach, gastrointestinal junction and distal esophagus and investigated their association with clinical data, including GC molecular subtypes." (PMID 34115237, 2021). "Therefore, FHOD1 ultimately leads to a state of immunosuppression in TME, providing favorable conditions for the growth and spread of tumor cells." (PMID 40364836, 2025). "Importantly, this increase of FHOD1 expression is seen in clinical cancers, in which EMT contributes to dissemination of tumours and subsequent treatment failure." (PMID 24086398, 2013). "Importantly, the highest FHOD1 expression was seen in areas, where cancer-related EMT is thought to occur in vivo, i.e. at the invasive front in elongated spindle-shaped tumour cells." (PMID 24086398, 2013). "In addition, we show that FHOD1 upregulation occurs during cancer cell EMT in vivo, which indicates that FHOD1 may contribute to tumour progression." (PMID 24086398, 2013). "The expression of FHOD1 and FMNL1 proteins was characterized in GC cells, and in non-neoplastic and malignant tissues utilizing tumor microarrays of intestinal GC representing different molecular subtypes." (PMID 34115237, 2021).
cancer (8 papers, 2012 to 2025). A tumor composed of atypical neoplastic, often pleomorphic cells that invade other tissues. "Specifically, FHOD1 regulates the function and activity of T-lymphocytes, cancer-associated fibroblasts (CAF), and B-cells through PDL1, which in turn affects the process of immune escape and immunosuppression in tumors." (PMID 40364836, 2025). "Thus, the identification of FHOD1 and its associated signaling networks underlying cell death would provide a suitable basis to sensitize cancer cells to cell death‐based therapeutic strategies." (PMID 37211949, 2023). "Recently, aberrated FHOD1 has been proven to be participate in several cancer‐associated processes." (PMID 37211949, 2023). "Taken together, these studies suggest that FHOD1 may mediate cytoskeletal changes and migratory properties in cancer-associated EMT of versatile cancer types." (PMID 24086398, 2013). "Similar to the role of FHOD1 in cancer progression, IRF7 is critical in the development and metastasis of tumors." (PMID 41262249, 2025). "FHOD1 plays a critical role in cancer progression, enhancing epithelial-mesenchymal transition (EMT), cell migration, and ECM degradation." (PMID 41262249, 2025). "Reduction of FHOD1 expression in these cancer cells decreases cell proliferation, colony formation in vitro, cell migration, and invasiveness." (PMID 37215084, 2023). "High levels of FHOD1 promoted cancer cell migration and invasion by inducing the ability of epithelial‐mesenchymal transition in squamous cell carcinoma." (PMID 37211949, 2023). "This can lead to an overestimation of the cancer cell-specific mRNA expression, while in our approach, we only analyzed cancer cell-specific FHOD1 and FMNL1 staining and disregarded the strongly stained immune cells from our scoring results." (PMID 34115237, 2021). "Previous studies by us and others implicate FHOD1 as an essential participant in cancer cell migration, invasion, and stress fiber formation." (PMID 34115237, 2021). "RNA analyses are typically performed from tissue bulk containing not only cancer cells but also mesenchymal cells, including FHOD1 and FMNL1 expressing immune cells." (PMID 34115237, 2021). "The role of FHOD1 in epithelially derived cancer cells has previously been addressed in one publication." (PMID 24086398, 2013). "However, despite its established significance in cancer biology, the role of FHOD1 in AS remains poorly understood." (PMID 41262249, 2025). "This dual regulatory mechanism confers a unique biological function to FHOD1 in cancer." (PMID 40364836, 2025). "Thus, the role of FHOD1 in malignant tumors is not limited to the promotion of EMT, it further exacerbates the immune escape phenomenon in tumors by upregulating PDL1 expression." (PMID 40364836, 2025). "Thus, it is likely that one of the key mechanisms for how upregulated FHOD1 expression promotes cancer progression is through increased SRF activity." (PMID 37215084, 2023). "In cancer cells, FHOD1 and FMNL1 showed different intensities of cytoplasmic expression." (PMID 34115237, 2021). "Whether increased expression of FHOD1 occurs in SCC in other locations or other types of cancer in general, is an important question that remains to be addressed." (PMID 24086398, 2013). "Finally, FHOD1 depletion reduced the ability of EMT cancer cells to form invadopodia and to degrade extracellular matrix." (PMID 24086398, 2013). "FHOD1-depleted cells invaded less efficiently than control cells (p<0.05), indicating that FHOD1 is relevant not only for migration in 2D conditions but also for invasive capacity of cancer cells." (PMID 24086398, 2013). "Four cancer-related hub genes (CRGs) were identified: Interferon Regulatory Factor 7 (IRF7), Formin Homology 2 Domain Containing 1 (FHOD1), Tumor Necrosis Factor (TNF), and Zinc Finger SWIM Domain Containing 3 (ZSWIM3)." (PMID 41262249, 2025).
cancer (continued). "The resulting identification of FHOD1 and IRF7—two genes previously recognized for their roles in cancer pathogenesis—points to shared molecular pathways between oncogenesis and advanced atherogenesis." (PMID 41262249, 2025). "we speculate that FHOD1 could trigger a series of downstream events by activating the STAT3 signaling pathway, which in turn promotes cancer cell invasion and metastasis." (PMID 40364836, 2025). "Although the immunohistochemical results and in silico mRNA profile suggested minimal FHOD1 expression in epithelial cell types, our transcriptomics results and GeneSapiens bioinformatics survey of carcinomas (not shown) indicated moderate mRNA levels in certain cancers." (PMID 24086398, 2013). "In contrast to FHOD1, FHOD3 upregulation has not been reported in cancer cells." (PMID 37215084, 2023).
infection (1 paper, 2016). The state of being infected such as from the introduction of a foreign agent such as serum, vaccine, antigenic substance or organism. "To confirm our results, we also examined infection by microscopy after depletion of FHOD1, FMNL3, GRID2IP or INF2; all four decreased bacterial uptake, though depletion of FMNL3 had the weakest effect." (PMID 27152864, 2016).
FHOD1 also shares sentences with these, for which no sentence is quoted: clear cell renal cell carcinoma (2 papers); mastitis (1); nasopharyngeal carcinoma (1); oral squamous cell carcinoma (1); pancreatic adenocarcinoma (1); thyroid cancer (1); thyroid tumor (1).